PRR13 (proline rich 13)
Description:
Negatively regulates TSP1 expression at the level of transcription. This down-regulation was shown to reduce taxane-induced apoptosis.
Synonyms: TXR1; FLJ23818; DKFZP564J157
Tractability: No criterion of Open Targets' tractability assessment is met for any kind of drug.
Gene: Protein-coding gene on chromosome 12 (53,441,308 to 53,446,660, forward strand). Ensembl gene ENSG00000205352.
Subcellular location: Nucleus
Subcellular location (Human Protein Atlas): Nucleoplasm; Cytosol; Vesicles
Gene Ontology:
Molecular function: protein binding
Cellular component: nucleoplasm; nucleus
Genetic constraint (gnomAD): Loss-of-function variants: 7 observed, 9.7 expected, observed/expected ratio (o/e) 0.72, 90% interval 0.41 to 1.35. That is too few expected variants to judge how well the gene tolerates losing a copy. Missense variants: 136 observed, 147.09 expected, observed/expected ratio (o/e) 0.92, 90% interval 0.8 to 1.07. Synonymous variants: 41 observed, 49.24 expected, observed/expected ratio (o/e) 0.83, 90% interval 0.65 to 1.08.
Homologues: Orthologues: chimpanzee PRR13 (91% identical), macaque PRR13 (90% identical), dog PRR13 (78% identical), pig PRR13 (69% identical).
Diseases named in the same sentence as PRR13 in open-access papers:
PRR13 is named in the same sentence as 17 diseases in open-access papers, as found by Europe PMC text mining. Sharing a sentence is not in itself a finding about the gene and the disease. The quoted sentences say what the papers report.
breast carcinoma (2 papers, 2020 to 2025). "In conclusion, our findings suggest that PRR13 overexpression is associated with an immunosuppressive phenotype in breast cancer, potentially promoting tumor progression through the modulation of immune cell infiltration." (PMID 40099041, 2025). "The PRR13 gene, associated with taxol resistance and the progression of various cancers, remains under-characterized in breast cancer." (PMID 40099041, 2025). "PRR13 is overexpressed in patients with breast cancer and is associated with patient survival." (PMID 40099041, 2025). "This research provides an important understanding of the potential function of PRR13 in the development and prediction of breast cancer outcome." (PMID 40099041, 2025). "In this study, the PRR13 gene was found to be overexpressed in malignant breast tissue compared to healthy breast tissue, suggesting a significant role for PRR13 in breast cancer progression." (PMID 40099041, 2025). "This study aimed to investigate the role of PRR13 in breast cancer and its potential as a prognostic biomarker." (PMID 40099041, 2025). "Our study further investigated the relationship between PRR13 expression and various clinical and pathological characteristics of breast cancer patients." (PMID 40099041, 2025). "In our current research, we observed an increase in the expression of PRR13 in breast cancer tissue." (PMID 40099041, 2025). "Immunohistochemistry showed that 44.4% of breast cancer samples had decreased levels of PRR13, while 55.6% had increased levels." (PMID 40099041, 2025). "Th17 cells, which were also positively correlated with PRR13 expression, are considered to be pro-tumorigenic immune cell types in the context of breast cancer." (PMID 40099041, 2025). "Neutrophils, another immune cell type that we found to be positively correlated with PRR13, play a significant role in breast cancer development." (PMID 40099041, 2025). "Analysis of the TCGA database revealed significant upregulation of PRR13 expression across 12 different cancer types, including breast cancer." (PMID 40099041, 2025). "Additionally, we investigated the relationship between PRR13 mRNA expression and immune cell infiltration in breast cancer (BRCA) using two methodologies." (PMID 40099041, 2025). "The univariate analysis model revealed that clinical stage (HR = 0.595, p = 0.039), ER expression (HR = 2.192, p = 0.008), PR expression (HR = 2.137, p = 0.011), and PRR13 expression (HR = 0.449, p = 0.008) showed prognostic implication for the predication of breast cancer." (PMID 40099041, 2025). "In conclusion, PRR13 expression is upregulated in breast cancer tissues and may serve as a valuable prognostic indicator for breast cancer patients, potentially impacting patient survival and therapeutic strategies." (PMID 40099041, 2025). "However, the role of PRR13 in breast cancer remains to be fully elucidated." (PMID 40099041, 2025). "To determine the functions of PRR13 in breast cancer, we first investigated the expression of PRR13 in 20 breast cancer tissues and 20 adjacent non-cancerous tissues by RT-qPCR." (PMID 40099041, 2025). "The results revealed that compared with adjacent non-cancerous tissues, the expression level of PRR13 mRNA was elevated in breast cancer tissues." (PMID 40099041, 2025). "However, to the best of our knowledge, PRR13 expression and function in breast cancer has not been elucidated." (PMID 40099041, 2025). "Knockdown of other upregulated ABC genes including PRR13, EGLN3, HSD11B2, and MATN3 also inhibited the proliferation of various breast cancer cell lines (data not shown)." (PMID 32539762, 2020).
non-small cell lung carcinoma (2 papers, 2011 to 2025). A group of at least three distinct histological types of lung cancer, including non-small cell squamous cell carcinoma, adenocarcinoma, and large cell carcinoma. "The expression levels of PRR13 have been observed to vary in different types of cancer, including nasopharyngeal carcinoma, gastric cancer and non-small cell lung cancer, with its mRNA levels in tumour tissue serving as a reliable prognostic marker." (PMID 40099041, 2025).
prostate carcinoma (2 papers, 2011 to 2025). A carcinoma that arises from epithelial cells of the prostate gland. "Another mechanism of taxane resistance, which has been recently described, suggests that overexpression of a previously unknown gene, the taxol resistance gene 1 (TXR1) or proline rich 13 (PRR13), prevents apoptosis in a human prostate cancer cell line." (PMID 21157449, 2011).
bladder cancer (1 paper, 2023). "The results showed thatPRR13 had the minimum negative score, compared withZNF330 andCHURC1 in 28 bladder cancer cell lines, suggesting that knockout ofPRR13 had the most significant inhibitory effect on the viability of bladder cancer cells.PRR13 was further included in the follow-up study." (PMID 37936490, 2023).
lymph node metastasis (1 paper, 2025). "Immunohistochemistry demonstrated high PRR13 expression in 55.6% of cancer cases, particularly associated with advanced clinical stage and lymph node metastasis." (PMID 40099041, 2025).
malaria (1 paper, 2025). Malaria is a serious and sometimes fatal disease caused by a parasite that commonly infects a certain type of mosquito which feeds on humans. "Thus, while cMaf is critical for Tfh differentiation in experimental malaria, Myo1f and Prr13, although transcriptionally upregulated, are unnecessary for effector or memory CD4+ T cell responses." (PMID 40132035, 2025). "In this study, we utilised existing scRNA-seq data from a mouse model of blood-stage malaria to hypothesise possible roles for Myo1f and Prr13 in CD4+ T cells." (PMID 40132035, 2025). "Taken together, our analysis revealed Myo1f and Prr13 expression were upregulated and maintained in specific effector and memory CD4+ T cell subsets during experimental malaria." (PMID 40132035, 2025). "Thus, in summary, we have discovered that cMaf is critical in experimental malaria for the early differentiation of Tfh cells, while Myo1f and Prr13 play no role in the biology of Plasmodium-specific CD4+ T cells during blood-stage infection." (PMID 40132035, 2025).
metastasis (1 paper, 2025). The spread or migration of cancer cells from one part of the body (where they first appeared) to another. "The observed association of elevated PRR13 levels with more severe pathological features, including later stage disease and lymph node metastasis, underscores its potential as a prognostic biomarker to help identify patients with more virulent tumour profiles." (PMID 40099041, 2025).
migraine (1 paper, 2023). "For kidney function, 19 significant tissue–gene pairs were found for migraine and eGFR using GTEx tissues, including four genes (TREX1, SHISA5, PRR13, TMA7) mainly expressed in tissues of the nervous and cardiovascular system." (PMID 37306871, 2023).
cancer (6 papers, 2009 to 2025). A tumor composed of atypical neoplastic, often pleomorphic cells that invade other tissues. "Prr13/Txr1 encodes for a nuclear protein and likely transcriptional regulators, whose up-regulation in cancer is reported to promote resistance to chemotherapy drugs known as taxanes." (PMID 40132035, 2025). "The increased presence of PRR13 in malignant breast tissue compared to surrounding healthy tissue suggests a role in cancer progression." (PMID 40099041, 2025). "By analyzing the gene expression of 37 types of cancers in TCGA, we demonstrate the potential role of PRR13 in carcinogenesis." (PMID 40099041, 2025). "Prr13/Txr1 is reported to transcriptionally regulate sensitivity to anti-cancer drugs." (PMID 40132035, 2025). "Our study provides new insights into how PRR13 overexpression affects the cancer immune landscape." (PMID 40099041, 2025). "The association between elevated PRR13 levels and reduced survival in patients with aggressive forms of cancer suggests that PRR13 may be a promising target for therapeutic intervention in such cases." (PMID 40099041, 2025). "Studies have shown that PRR13 plays an important role in chemotherapeutic resistance by reducing the expression of the pro-apoptotic gene thrombospondin-1 (TSP1), thereby inhibiting taxol-induced apoptosis in cancer cells." (PMID 40099041, 2025). "It has been shown that Prr13 upregulation in certain cancer cells leads to a significant downregulation of TSP-1, a protein known for its anti-angiogenic and pro-apoptotic properties, which binds to cell surface receptor CD47 and triggering caspase-independent apoptosis of cancer cells." (PMID 40132035, 2025).
tumor (4 papers, 2011 to 2025). "Our ssGSEA and CIBERSORT analyses show that PRR13 expression is intricately linked to the tumor microenvironment." (PMID 40099041, 2025). "Subgroup analysis underscored the prognostic significance of PRR13 in aggressive tumor subtypes, with particularly strong associations observed in T3, N1-3, and moderately to poorly differentiated tumors." (PMID 40099041, 2025). "Mast cells, which showed a positive correlation with PRR13, are known to be involved in both tumor proliferation and survival, as well as in the promotion of tumor invasion and metastasis." (PMID 40099041, 2025). "Subgroup analysis revealed differential prognostic implications of PRR13 expression in distinct tumor subtypes, further emphasizing its role in tumor progression." (PMID 40099041, 2025). "The CCLE data allowed for the observation ofPRR13 expression in multiple cell lines (available online).PRR13 was aberrantly expressed in multiple tumor tissues and adjacent normal tissues." (PMID 37936490, 2023). "Considering that GO and KEGG enrichment analysis showed that PRR13 may be involved in tumour immune response, we further analysed the relationship between PRR13 mRNA expression and the level of immune cell infiltration in BRCA using ssGSEA and CIBERSORT." (PMID 40099041, 2025). "PRR13 expression was strongly associated with OS duration in patients in the T3, N1-3 and grade 2–3 subgroups, but not in patients in the T1-2, N0 and grade 1 subgroups, suggesting that PRR13 may play a more important prognostic role in patients with more aggressive tumour behaviour." (PMID 40099041, 2025). "Conversely, the negative correlation between PRR13 and Th1 cells, which are known to enhance anti-tumor immune responses through the production of interferon-γ (IFN-γ) and other cytokines, suggests that PRR13 overexpression might suppress the function of these anti-tumor immune cells." (PMID 40099041, 2025). "Similarly, the negative correlation with CD4+ memory T cells, which play a crucial role in anti-tumor immunity and can suppress tumor growth by enhancing anti-tumor immune responses, indicates that PRR13 might inhibit their function within the tumor microenvironment." (PMID 40099041, 2025). "Validation studies confirmed elevated PRR13 expression in tumor tissue compared to adjacent non-cancerous tissue." (PMID 40099041, 2025).
infection (2 papers, 2020 to 2025). The state of being infected such as from the introduction of a foreign agent such as serum, vaccine, antigenic substance or organism. "Prr13 was modestly expressed in naïve PbTIIs, and strongly upregulated by all PbTIIs and polyclonal counter parts (Fig 1Ai-iii and 1Bi-ii), with the magnitude and frequency of expression largely maintained by PbTIIs until day 28 post-infection and treatment (Fig 1Aii-iii)." (PMID 40132035, 2025). "After re-infection, expression of Myo1f and Prr13 was retained, without evidence of further up-regulation in PbTIIs (Fig 1Ci-ii) or polyclonal cells (Fig 1Di-ii)." (PMID 40132035, 2025).
PRR13 also shares sentences with these, for which no sentence is quoted: lung adenocarcinoma (2 papers); dyslipidemia (1); gastric cancer (1); ischemia reperfusion injury (1); ovarian carcinoma (1); squamous carcinomas (1).